AXL (AXL receptor tyrosine kinase)
Diseases named in the same sentence as AXL in open-access papers (continued):
Sharing a sentence is not in itself a finding about the gene and the disease.
prostate carcinoma (continued). "Thus, this work indicates that elevated AXL expression can mediate docetaxel resistance and provide a rationale for the clinical evaluation of anti-AXL therapeutics for the treatment of docetaxel-resistant prostate cancer." (PMID 28455956, 2017). "Taken together, more studies may be necessary to determine the exact roles ABCB1 plays in AXL-mediated resistance to docetaxel in prostate cancer." (PMID 28455956, 2017). "Having identified that AXL was overexpressed in the PC3-DR and DU145-DR cells, we further investigated whether genetic upregulation of AXL led to docetaxel resistance in prostate cancer cells." (PMID 28455956, 2017). "Collectively, our findings suggest that ABCB1 upregulation may be another mechanism of AXL-mediated docetaxel resistance in prostate cancer." (PMID 28455956, 2017). "The NF-κB pathway may also be involved in AXL-induced EMT phenotype in docetaxel-resistant prostate cancer." (PMID 28455956, 2017). "Activation of AXL often occurs upon binding to Gas6, including in prostate cancer." (PMID 28455956, 2017). "Therefore, our findings suggest that induction of EMT contributes to the AXL-mediated acquired docetaxel resistance in prostate cancer." (PMID 28455956, 2017). "Indeed, AXL has been shown to be up-regulated in metformin-resistant prostate cancer cells." (PMID 35752711, 2022). "Interestingly, AXL is upregulated and activated in docetaxel-resistant prostate cancer cell lines, and AXL blockade in these cells, either by siRNA targeting or treatment with the non-specific tyrosine kinase inhibitor amuvatinib (MP470), induced apoptosis and reduced cell migration and invasion." (PMID 33105713, 2020). "However, the role of AXL expression in docetaxel resistance in prostate cancer is yet unclear." (PMID 28455956, 2017). "Their findings revealed a positive correlation between AXL expression, TGF-β, and its receptor in disseminated prostate cancer cells, indicating a crucial crosstalk between TGF-β and the Gas6/Axl signaling pathways that regulate tumor dormancy." (PMID 38795254, 2024). "Our current study exploited a novel therapeutic intervention targeting AXL, Notch1, Myc, or SIRT1 in an attempt to improve the management of androgen-refractory prostate cancers." (PMID 37960146, 2023). "Therefore, while preclinical data indicate that AXL is a promising therapeutic target, particularly within docetaxel-resistant disease, more research is required to establish the role of AXL activation in prostate cancer, and to determine whether PTEN status is a predictive marker for AXL activity." (PMID 33105713, 2020). "In prostate cancer, it has been demonstrated that GAS6/AXL and transforming growth factor-beta 2 (TGF-β2) signaling regulates tumor cell dormancy." (PMID 31694201, 2019). "Furthermore, genetic, or pharmacologic inhibition of AXL was shown to revert EMT in pancreatic and prostate cancer cells and to modulate the expression of nucleoside transporters playing a role in chemotherapeutic response." (PMID 35158733, 2022). "Collectively, the data demonstrate that AXL is clearly upregulated and the constitutive activation of AXL is independent of Gas6 in docetaxel-resistant prostate cancer cells." (PMID 28455956, 2017). "Taken together, these results indicate that AXL overexpression and activation, independent of Gas6, is closely related to docetaxel resistance in prostate cancer." (PMID 28455956, 2017). "In this study, we demonstrate that AXL is overexpressed and activated independent of Gas6 in docetaxel-resistant prostate cancer cells (PC3-DR and DU145-DR)." (PMID 28455956, 2017). "AXL and PDGFR are associated with aggressive breast, kidney, lung, and prostate cancers, suggesting that c-MET-AXL-PDGFR may be clinically relevant to BCa." (PMID 26225770, 2015).
prostate carcinoma (continued). "One study showed successful labeling with the use of an anti-human monoclonal AXL antibody radiolabelled with I125 via SPECT/CT imaging in mice xenografted with AXL-high and AXL-low pancreatic and prostate cancer cell lines and uptake appeared to correlate closely with IHC findings." (PMID 25337673, 2014). "AXL knockout in prostate cancer cells does not alter dormancy induction." (PMID 41091336, 2025). "Consistent with a role of AXL in RNASE4-induced prostate cancer growth, we found that RNASE4 knockdown or treatment with RNASE4 mAb in xenograft animal models resulted in a reduction of AXL phosphorylation without affecting the total AXL levels in the tumor tissues." (PMID 35752711, 2022).
hepatocellular carcinoma (30 papers, 2015 to 2025). A malignant tumor that arises from hepatocytes. "Elevated soluble AXL (sAXL) has been reported to be associated with disease progression in hepatocellular carcinoma, renal cancer, neurofibromatosis type 1 and inflammatory diseases." (PMID 31917795, 2020). "The AXL promoter contains four TEAD binding sites, and YAP binds to the AXL promoter region in hepatocellular carcinoma." (PMID 37835395, 2023). "Cabozantinib is a tyrosine kinase inhibitor, known for inhibiting VEGFR, MET, and AXL, already in clinical use against multiple kinds of malignancies like hepatocellular carcinoma, sarcoma, and renal-cell carcinoma." (PMID 35719911, 2022). "AXL, a member of the TAM family, is a promising therapeutic target due to its elevated expression in advanced hepatocellular carcinoma (HCC), particularly in association with acquired drug resistance." (PMID 34948046, 2021). "sAXL, the cleaved extracellular domain of AXL, is being explored as a potential biomarker in certain cancers and other inflammatory conditions, such as in hepatocellular carcinoma, neurofibromatosis type 1, and in NSCLC." (PMID 32148495, 2020). "It is thought that glycosylation is important for AXL's function, as inhibition of glycosylation results in a decrease in cell proliferation and invasion in hepatocellular carcinoma cell lines and in metastasis formation in vivo." (PMID 32148495, 2020). "For example, SKI606 (Bosutinib), a multi-kinase inhibitor targeting AXL, has been shown to reduce AXL-specific invasiveness in hepatocellular carcinoma cells and is in Phase 1 and 2 clinical trials for metastatic breast cancer." (PMID 27764792, 2016). "In that respect, Cabozantinib inhibits tyrosine kinases, including the VEGF receptors 1, 2, and 3, MET, and AXL, which are involved in the progression of hepatocellular carcinoma and the development of resistance to sorafenib, which is the conventional first-line treatment for advanced HCC." (PMID 38068521, 2023). "AXL expression was significantly correlated with multiple clinicopathological characteristics of tumor invasiveness, and could predict poor prognosis in hepatocellular carcinoma (HCC) patients after partial hepatectomy." (PMID 34838035, 2021). "This was an interesting observation as previous studies have shown that YAP may regulate AXL expression in lung adenocarcinomas and in hepatocellular carcinoma by way of TEAD binding to the promoter region of the AXL gene." (PMID 28680534, 2017). "It was reported that soluble AXL could outperform AFP in diagnosing very early hepatocellular carcinoma and correlated with tumor stage as well as patient survival in renal cell carcinoma." (PMID 27015365, 2016). "AXL was recently identified as a direct transcriptional target of HIF-1 and HIF-2 in tumor cells where it mediates the prometastatic behavior of HIF signaling in von Hippel Lindau (VHL)-deficient renal cell carcinoma and hypoxic hepatocellular carcinoma cells." (PMID 27834845, 2016). "Overexpression of AXL has also been found in a variety of other cancers, including clear cell renal cell carcinoma (ccRCC), hepatocellular carcinoma (HCC), and cholangiocarcinoma (CCA), which is associated with poor prognosis of these cancer patients." (PMID 37328828, 2023). "Up-regulation of AXL is well documented in hepatocellular carcinoma (HCC), and contributes to HCC cell line proliferation, migration and invasion, through activation of AKT and MAPK signalling pathways." (PMID 26313459, 2015). "In hepatocellular carcinoma, studies have shown that YAP1 knockdown results in reduced AXL activity, leading to decreased cell invasion." (PMID 39924521, 2025). "AXL was identified as a downstream effector of TGF-β and modulates expression of TGF-β/SMAD-dependent target genes involved in cell migration in hepatocellular carcinoma." (PMID 35813203, 2022). "Akin to AXL, PROS1 expression was recently found to be inversely correlated to miR-34a in HepG2 hepatoma cells." (PMID 28118606, 2017).
hepatocellular carcinoma (continued). "In hepatocellular carcinoma (HCC), the molecular collaboration of AXL/14-3-3ζ and TGF-β/Smad signaling on cancer progression has been demonstrated." (PMID 27172793, 2016). "AXL is involved in the development of fibrosis, linking AXL with non-alcoholic fatty liver disease (NAFLD)/non-alcoholic steatohepatitis (NASH) and hepatocellular carcinoma (HCC)." (PMID 35158733, 2022).
COVID-19 (29 papers, 2020 to 2025). A disease caused by infection with severe acute respiratory syndrome coronavirus 2. "Serum ACE2/AXL levels in COVID-19 patients were detected by enzyme-linked immunosorbent assay (ELISA) at different time points post-COVID-19 infection, including days 0-7, 8-15, 31-179 and >180 days." (PMID 38799467, 2024). "Given the low expression levels of ACE2 in respiratory tissues, the COVID-19 pathogenesis is likely also mediated by other spike protein receptors such as AXL." (PMID 40649848, 2025). "A decrease in tyrosine-protein kinase receptor UFO (AXL) in AlvMφ of COVID-19 patients is thought to disturb their phagocytic function." (PMID 39796262, 2025). "The level of AXL also decreased in the initial cohort of COVID-19 patients, which was first noted in our research." (PMID 38799467, 2024). "In our study, not only ACE2, but also serum AXL, derived from another receptor of COVID-19, also seem to be a potential molecular marker for predicting COVID-19 progression." (PMID 38799467, 2024). "In this study, we developed nanoparticles incorporated with quercetin and ACE2-membrane as a novel ACE2 and AXL-targeting therapy for COVID-19 treatment." (PMID 38609998, 2024). "Our study aimed to analyze the serum levels of ACE2 and AXL in individuals during the acute phase of COVID-19, in comparison to healthy individuals." (PMID 38799467, 2024). "Compared with the uninfected group, the levels of ACE2 and AXL in the COVID-19 group were decreased, and the SARS-COV-2 IgG level was increased." (PMID 38799467, 2024). "Nonetheless, research on circulating levels of soluble ACE2 and AXL and their implications in COVID-19 patients remains limited." (PMID 38799467, 2024). "Our results also show that AXL is decreased in the lung tissue of patients with severe COVID-19, which suggests that there is an overactivation of inflammasomes." (PMID 37113134, 2023). "Given this, AXL is an attractive therapeutic target, and its inhibitors are being tested in cancer and COVID-19 clinical trials." (PMID 35622156, 2022). "In summary, these results support a relevant role of the GAS6/AXL system in the immune response against COVID-19, suggesting them as early markers of disease prognosis and GAS6/AXL targeting as plausible clinical therapy for COVID-19 patients." (PMID 33810394, 2021). "Second, cfDNA, NE, histones and GAS6/AXL are related to the severity of illness and reflect organ dysfunction in severe COVID-19." (PMID 34344929, 2021). "AXL is a candidate receptor for SARS-CoV-2, particularly in the respiratory system, and the GAS6/AXL axis is targeted in current clinical trials against COVID-19." (PMID 33810394, 2021). "In pre-DCs, an up-regulation of the stem cell marker c-KIT was detected in severe COVID-19, and AXL was decreased in response to infection." (PMID 33479167, 2021). "The AXL expression level is well correlated with SARS-CoV-2 S level in bronchoalveolar lavage fluid cells from COVID-19 patients." (PMID 33420426, 2021). "Highlighting the importance of the treatment schedule, recent data revealed that GAS6 and AXL significantly increased in plasma of COVID-19 patients as compared to controls, while GAS6 decreased over time in patients surviving to 30 days post ICU admission." (PMID 32998369, 2020). "Another receptor for SARS-CoV2 potentially linking COVID-19 to cancer is AXL (Anexelekto)." (PMID 41375068, 2025). "In addition to serving as a potential SARS-CoV-2 receptor, AXL has been proposed as a molecular marker for COVID-19 progression." (PMID 40649848, 2025). "The SARS-COV-2 enters the cytoplasm through ACE2 and AXL-mediated endocytosis, which may cause the decrease in serum ACE2 and AXL levels in the initial cohort of COVID-19 patients." (PMID 38799467, 2024). "Considering serum AXL plays a major role in regulating inflammation, AXL may play an important role in the severe progression of COVID-19." (PMID 38799467, 2024). "The levels of serum ACE2 and AXL correlate with COVID-19 severity." (PMID 38799467, 2024).
COVID-19 (continued). "In summary, serum AXL seems to be a superior biomarker for COVID-19." (PMID 38799467, 2024). "Therefore, these nanoparticle preparations should be ideal for targeting ACE2 and AXL in the COVID-19 treatment." (PMID 38609998, 2024). "In our study, the level of serum AXL not only is correlated with the development of COVID-19, but also can provide early warning of clinical deterioration in the first week after infection, suggesting that it is a superior biomarker for COVID-19." (PMID 38799467, 2024). "In addition, we sought to investigate the serum levels of ACE2 and AXL in patients at different time points post-COVID-19 infection and determine if these levels correlate with COVID-19 progression." (PMID 38799467, 2024). "AXL appears to be a superior potential molecular marker for predicting COVID-19 progression." (PMID 38799467, 2024). "Importantly, pharmacological inhibition of AXL also shows promise as a potential COVID-19 therapy, and bemcentinib is currently being tested for the treatment of patients with COVID-19." (PMID 35444538, 2022). "Whereas AXL, which is important for neutrophil infiltration and COVID-19 therapy via regulating TGF-β and PI3K signaling pathways, also works as a candidate receptor for SARS-CoV-2 entry, was significantly reduced about 3-fold in infected CMs as compared with the healthy control." (PMID 35903092, 2022). "Notably, one of the AXL inhibitors, R428 (bemcentinib), is currently being tested in a clinical trial in COVID-19 patients." (PMID 35622156, 2022). "If this is the case, then AXL could constitute a novel therapeutic target for future antiviral COVID-19 medications to mitigate the systemic manifestations of COVID-19." (PMID 35401519, 2022). "In this study, we systematically reviewed the relationship between viral cell surface receptors (ACE2, AXL, CD147, DC-SIGN, L-SIGN and DPP4) and SARS-CoV-2 infection risk, and emphasized the implications of ACE2 on SARS-CoV-2 infection and COVID-19 pathogenesis." (PMID 34867819, 2021). "AXL inhibition is in clinical trial for COVID-19 treatment (ACCORD-2-001)." (PMID 33810394, 2021). "First, cfDNA, NE, histones and GAS6/AXL are activated in severe COVID-19." (PMID 34344929, 2021). "cfDNA, H3, NE, GAS6 and AXL were increased in COVID-19 patients compared to controls." (PMID 34344929, 2021). "Besides, expression levels of AXL are closely correlated with SARS-CoV-2 S protein levels in bronchoalveolar lavage fluid cells from COVID-19 patients." (PMID 34867819, 2021). "In the bronchoalveolar lavage fluid cells of COVID-19 patients, the expression level of AXL is highly correlated with the level of SARS-CoV-2 S and AXL is highly expressed in almost all types of respiratory system cells including lung type I/II epithelial cells, basal cells, and fibroblasts." (PMID 34295915, 2021). "Because of the possible contribution of GAS6 to neutrophil and platelet recruitment and aggregation, these observations may suggest GAS6/AXL as a promising target for the prevention and treatment of pulmonary failure and thrombotic complications of COVID-19." (PMID 32998369, 2020). "However, the AUC of a combination of ACE2 + AXL (0.741) was not higher than AXL alone, suggesting that AXL had a better ability to predict the risk of COVID-19." (PMID 38799467, 2024). "Therefore, serum AXL seems to be a better predictor for COVID-19." (PMID 38799467, 2024). "The serum ACE2, AXL, and SARS-COV-2 IgG/IgM were compared between a cohort of 71 uninfected individuals and 148 COVID-19 patients with positive nucleic acid in 0-7days." (PMID 38799467, 2024). "In the second week after laboratory-confirmed COVID-19, the levels of serum ACE2 and AXL in the severe group (n=93) were significantly higher than that in the non-severe group (n=67), while SARS-COV-2 IgG was significantly lower." (PMID 38799467, 2024). "Do the levels of ACE2, AXL and SARS-COV-2 IgG/IgM in COVID-19 patients return to an uninfected state after 180 days?" (PMID 38799467, 2024).